CPVL (carboxypeptidase vitellogenic like)
Description:
May be involved in the digestion of phagocytosed particles in the lysosome, participation in an inflammatory protease cascade, and trimming of peptides for antigen presentation.
Synonyms: hVLP
Tractability: Antibody: UniProt predicts a signal peptide or a membrane-spanning region. PROTAC: ubiquitination databases record sites on it; its protein half-life has been measured.
Gene: Protein-coding gene on chromosome 7 (28,994,636 to 29,195,451, reverse strand). Ensembl gene ENSG00000106066.
Subcellular location (Human Protein Atlas): Endoplasmic reticulum
Gene Ontology:
Molecular function: serine-type carboxypeptidase activity
Biological process: proteolysis
Cellular component: extracellular exosome
Genetic constraint (gnomAD): Loss-of-function variants: 25 observed, 35.94 expected, observed/expected ratio (o/e) 0.7, 90% interval 0.51 to 0.97. The upper end of that interval is the gene's LOEUF score, 0.97, which puts it in group 4 of 6, group 1 being the genes least tolerant of losing a copy. Missense variants: 413 observed, 443.1 expected, observed/expected ratio (o/e) 0.93, 90% interval 0.86 to 1.01. Synonymous variants: 144 observed, 163.91 expected, observed/expected ratio (o/e) 0.88, 90% interval 0.77 to 1.01.
Homologues: Orthologues: chimpanzee CPVL (98% identical), macaque CPVL (90% identical), guinea pig CPVL (80% identical), rabbit CPVL (80% identical), dog CPVL (77% identical), pig CPVL (76% identical), mouse Cpvl (76% identical), rat Cpvl (75% identical), zebrafish cpvl (60% identical), tropical clawed frog cpvl (57% identical), Drosophila melanogaster CG4572 (42% identical). Paralogues in human: CTSA (26% identical), SCPEP1 (23% identical).